RNU6-768P (RNA, U6 small nuclear 768, pseudogene)
Gene: Small nuclear RNA gene on chromosome 12 (101,199,271 to 101,199,377, reverse strand). Ensembl gene ENSG00000207414.
Homologues: Orthologues: chimpanzee U6 (100% identical), macaque U6 (96% identical), dog U6 (85% identical), dog U6 (84% identical). Paralogues in human: RNU6-211P (92% identical), RNU6-1152P (90% identical), RNU6-333P (89% identical), RNU6-812P (89% identical), RNU6-15P (88% identical), RNU6-20P (88% identical), RNU6-1035P (87% identical), RNU6-1145P (87% identical), RNU6-16P (87% identical), RNU6-196P (87% identical), RNU6-25P (87% identical), RNU6-310P (87% identical), and 1290 more.